TNF (tumor necrosis factor)
Diseases named in the same sentence as TNF in open-access papers (continued):
Sharing a sentence is not in itself a finding about the gene and the disease.
colitis (continued). "Consistent with the high LPS load in serum, the expression level of inflammatory cytokines TNF-α, IL-1β, and IL-6 significantly increased in the colons of mice with DSS-induced colitis." (PMID 39272608, 2024). "Compared to the control group, the expression levels of the TNF-α (p < 0.001), IL-1β (p < 0.001), and IL-6 (p < 0.05) genes were significantly increased in the DSS-induced colitis group." (PMID 38474831, 2024). "An increased Nrf2 expression in the colorectal mucosa of mice along with a decreased expression of TNF-α, IL-1β, IL-6, IFN γ, NF-κB, COX2, and iNOS were also found after a 4 week supplementation with crocin in DSS-induced colitis." (PMID 38543230, 2024). "In trinitrobenzenesulfonic acid (TNBS)-induced colitis in rats, inosine was shown to reduce macroscopic injury, as well as levels of MDA, MPO, IL-1β and TNF-α in colonic tissue, in part, through the activation of A2AAR." (PMID 38474346, 2024). "The results show that CA effectively alleviated colitis, as evidenced by an increased colon length, lowered disease activity index (DAI) and histological scores, and decreased tumor necrosis factor-α (TNF-α) and interleukin-6 (IL-6) expression levels." (PMID 38255916, 2024). "To further elucidate the anti-inflammatory effects of HU308 in DSS-induced colitis, we measured the levels of several pro-inflammatory cytokines in chronic colon tissues, including IL-6, IL-1β, IL-17, MCP-1, TNF-α, and IFN-γ." (PMID 39682761, 2024). "Astaxanthin significantly suppressed the mucosal mRNA expression of pro-inflammatory cytokines, including IL-1β, IL-6, TNF-α, IL-36α, IL-36γ, and COX-2, in DSS colitis." (PMID 38672464, 2024). "At the same time, STAT3 knockout also reduced the differences in the expression of IL-6, TNF-α, and IL-1β, as well as ZO-1, occludin, BCL-2, and BAX in the colons of mice with colitis induced by different diets." (PMID 38233383, 2024). "In DSS-induced colitis, pre-treatment with DHA-PL and DHA-enriched triglyceride (DHA-TG) for 14 days downregulated pro-inflammatory IL-1β and TNF-α and upregulated anti-inflammatory IL-10 protein expressions." (PMID 38672464, 2024). "In fact, it was shown that the pasteurized preparation of A. muciniphila resulted in downregulation of inflammatory cytokines such as TNFα, Interferon-γ (IFNγ), IL-1β, IL-6, IL-8 and IL-33 with a marked improvement in DSS-induced colitis." (PMID 37370812, 2023). "Both in vitro and in vivo, the colitis increased NF-kB and NF-kB-p65, COX-2, iNOS, IL-1β, IL-6, and TNF-α activity, in addition to decreasing PPARγ expression." (PMID 36677021, 2023). "Since more inflammatory cells infiltration and elevated levels of TNF-α, IL-1β, and IL-6 were observed in colonic tissue of DSS-treated mice, we next examined changes of cellular components involved in the colitis with a special focus on macrophages." (PMID 37813835, 2023). "The present study proved PHI reduced the production and release of inflammatory factors such as IL-6, IL-1β, and TNF-α in both LPS-induced RAW264.7 cells and DSS-induced colitis mice." (PMID 36768559, 2023). "To address the functional role of P2Y1R in intestinal mucosal repair during colitis, we next evaluated the effect of inhibiting P2Y1R with its specific antagonist, MRS2179, on TNF-α-treated Caco-2 cell monolayers." (PMID 37781034, 2023). "Oral administration of the β-naphthoflavone (an AhR agonist) decreased the severity of colitis and the production of pro-inflammatory cytokines, such as TNF-α, IL-6, and IL-1β in DSS-induced colitis." (PMID 36672703, 2023). "CsA ameliorated histology damage and the histological scores, decreased inflammatory cytokines (TNF-α and IL-1β) expression and downregulated NE and citH3 expression of NETs-related proteins in DSS-induced colitis mice." (PMID 38093197, 2023). "ALA-rich sage oil ameliorates colitis by down-regulating pro-inflammatory genes, including IL-6, COX2, TNFα, IL-8, and iNOS." (PMID 37868958, 2023).
colitis (continued). "Next, we measured the expression levels of three selected cytokines, TNF-α, interleukin-6 (IL-6), and CXCL1/KC, in mouse serum to assess the possible anti-inflammatory effects of EVs on the DSS-induced colitis model." (PMID 37966243, 2023). "Consistent with more severe colitis in neutrophil-depleted mice, higher proportions of IFN-γ-, IL-17A- and TNF-α-expressing TCRγδ+CD8αα+ IELs were detected in these mice compared to WT controls." (PMID 36729914, 2023). "Alleviated the disruption of Intestinal barrier function, alleviated colitis symptoms, Inhibiting the Production of IL-6, TNF-R1, TNF-R2, and TNF-α." (PMID 37485519, 2023). "Compared with WT mice, S1PP2−/− mice had higher intestinal epithelial barrier integrity (manifested as increased expression of E-cadherin) and lower levels of TNF, IL-1β and IL-6 in intestinal tissue in the DSS-induced colitis mouse model." (PMID 37560160, 2023). "Previously, similar results reported that B. breve CCFM683 reduced colon inflammation by increasing colon length and reducing TNF-α, IL-1β and IL-6 expression in the colons of DSS-induced colitis mice." (PMID 36986118, 2023). "Oral administration of Cur-NPs can significantly reduce neutrophil infiltration and TNF-α, restore colon structure in DSS induced colitis mice." (PMID 37033644, 2023). "After adoptive transfer, production of pro-inflammatory cytokines, such as TNFα and p40, and macrophage-related chemokines, such as MCP-1 and MIP-1α, were increased with colitis development." (PMID 38012544, 2023). "Next, we investigated the effect of AM on claudin‐4 expression in the TNFα‐treated human colonic epithelial cell line, HCT116, which mimics the inflammatory condition of epithelial cells in colitis." (PMID 36799102, 2023). "In both CD4+ and CD8+ T cells, GSEA Hallmark pathway analysis identified significant enrichment of processes such as inflammatory responses, IL2/STAT5 signalling, allograft rejection, TNF signalling and apoptosis in CPI colitis." (PMID 37872166, 2023). "Eudragit RL PO nanoparticles loaded with SM (75 mg/kg/day) can significantly reduce TNF-α, IL-6 and MPO activity in colon tissues, improve macroscopic and histopathological scores of acetic acid-induced colitis mice." (PMID 37033644, 2023). "Overall, this panel identified IL-6, IL-22, IL-13, LT-α and TNF-α as upregulated inflammatory markers and CD40L as a downregulated marker of DSS-induced experimental acute murine colitis." (PMID 36672648, 2023). "Broccoli-derived exosome-like nanoparticles inhibited the expression of pro-inflammatory cytokines, such as TNF-α, IL-17 A, and INF-γ, in experimental mouse colitis by inhibiting the activation of dendritic cells (DCs) activation and inducing tolerant DCs." (PMID 37653406, 2023). "In any case, various TNF-α blockers, such as infliximab, etanercept, adalimumab and certolizumab, have been used as rescue therapy for steroid-refractory cases of ICI-induced colitis, arthritis and pneumonitis." (PMID 36900420, 2023). "TNF, IL1B, and IL6 were increased in Il17b-/- mice compared with WT in colitis in both protein and mRNA levels." (PMID 36814913, 2023). "TNF is a major proinflammatory cytokine that contributes to the pathogenesis of IBD in humans and experimental colitis in mice." (PMID 37598207, 2023). "Consistently, IHC staining also confirmed the downregulated expression of IL-1β, IL-6, TNF-α and COX-2 in colitis model of β6-KO mice." (PMID 37223685, 2023). "Others also demonstrate that inhibiting ILK abrogates NLRP3-mediated IL-1β production, that ILK knockdown reduces TNF-α production via NF-κB, and that ILK knockout in intestinal epithelial or myeloid cells reduces DSS-induced colitis in mice." (PMID 36930690, 2023). "Macrophages produce Tumor Necrosis Factor-Alpha (TNF-alpha), IL-6, CXCL1, and CXCL9/10 chemokines, thus resulting in the recruitment of additional T cells within the colon and exacerbation of colitis." (PMID 37239166, 2023).
colitis (continued). "Similar trends were observed for IL-22, IL-13, LT-α and TNF-α, with small increases measured within the 2% DSS group and significantly higher systemic levels when the colitis worsens within the 3–5% DSS groups." (PMID 36672648, 2023). "As a consequence, BMDA or DMMA administration reduced expression levels of inflammatory cytokines such as IL-1β and TNF-α in LPS-stimulated THP-1 cells in vitro and in tissues from DNBS-induced colitis and collagen-induced arthritis in vivo." (PMID 37153778, 2023). "Microbiota depletion resulted in a remarkable reversion of the colitis phenotype after MLT administration, including a counter-regulatory immune response, reduction in TNF and colon macrophages." (PMID 36838425, 2023). "In a mice model, TNF inhibitors concomitantly with combined CTLA-4 and PD-1 immunotherapy ameliorated colitis and improved antitumor efficacy, which provided clinically feasible strategies to dissociate efficacy and toxicity for cancer immunotherapy." (PMID 36950013, 2023). "extract combined with L. brevis inhibited TNF-α, IL-1β and IFN-γ production in the lymph nodes and spleens of 4% DSS-induced colitis mice." (PMID 36986118, 2023). "In contrast, several studies investigating hepatic tissue in colitis induction models with 3%, 4%, and 5% DSS reported increased levels of TNF-α and/or MPO activity and similarly to our work reduced levels of IL-10." (PMID 37577725, 2023). "Earlier studies considered T cell transfer mice colitis to be a Th1-mediated model because it resulted in the development of a large population of T cells producing IFN-γ and TNF-α." (PMID 37554552, 2023). "The repercussion of colitis on the hepatic inflammatory profile was investigated, through MPO activity and TNF-α and IL-10 levels." (PMID 37577725, 2023). "All treatment groups significantly reduced the proinflammatory cytokines “TNF-α and IL-1β” compared to the DSS-induced colitis group." (PMID 37545572, 2023). "Previous studies have shown that interferon-γ and TNFα induce TLR4 transcription, which in turn is required for the induction of cyclooxygenase 2 expression in DSS-induced colitis in mice." (PMID 36768553, 2023). "Meanwhile, the secretion of proinflammatory factors IL-1β, IL-6, TNF-α, and PGE2 was enhanced, as well as the levels of anti-inflammatory factor IL-10 were reduced in the serum of colitis rats, which was all reversed by EA treatment." (PMID 36910013, 2023). "Dietary supplementation with EGCG improved acetic acid-induced colitis, as indicated by colon mucosal damage index and histological scores, and decreased levels of NO, MDA, TNF-α, IFN-γ, p65, as well as increased superoxide dismutase (SOD) activity." (PMID 37298531, 2023). "On one hand, HEP10 suppressed the production of TNF-α, IL-1β, IL-6, inducible iNOS, and COX-2 in LPS challenged murine macrophage RAW264.7 cells, as well as in colons from DSS-induced colitis mice." (PMID 36771444, 2023). "Consistently, the protein levels of inflammatory cytokines TNF-α, IFN-γ, IL-1β, and IL-6 in the serum of MKO colitis mice were increased." (PMID 36635421, 2023). "MC-LR increased the expression of IL-6, IL-1β, TNF-α, and IL-1αin in the DSS-induced colitis model, thereby aggravating the inflammation." (PMID 37505716, 2023). "To complement our genetic and exogenous TNF supplementation models of OTULIN-dependent sensitivity, we evaluated colitis development in response to infection with the Salmonella enterica serovar Typhimurium (Salmonella)." (PMID 37598207, 2023). "Combined administration of SM and nano Se can improve anti-inflammatory and antioxidant capacity by reducing the expression of TNF-α, IL-1β, NF-κB, MPO, lipid peroxidation and protein carbonyl, finally relieve symptoms of TNBS-induced colitis." (PMID 37033644, 2023). "We recorded remarkable increase in DAI, histopathologic damage, serum TNF-α and IL-6 levels, and MPO activity in mice with DSS-induced colitis." (PMID 37111064, 2023).
colitis (continued). "Oral administration of C-SBLNs can reduce leukocyte infiltration, oxidative stress and proinflammatory cytokines (TNF-α), restore colon structure in DSS-induced colitis mice." (PMID 37033644, 2023). "IL-10 can suppress the secretion of pro-inflammatory cytokines, such as TNFα, to improve colonic inflammation in the DSS-induced colitis model." (PMID 37185924, 2023). "Numerous previous studies showed increased expression of inflammatory mediators (such as TNF-α, IL-6 and COX-2) in the brain following TNBS- or dextran sulfate sodium-induced colitis." (PMID 37371401, 2023). "The expressions of RFZ1, IL-6, TNF-α, and IL-1β were also increased in CD68+ macrophage detected by IF staining in the colon from mice with colitis." (PMID 37733446, 2023). "Oral administration with apigenin alleviated colon length shortening, decreased levels of colonic myeloperoxidase (MPO), alkaline phosphatase (AKP), TNF-α, IL-6, and restored intestinal microbiome in TNBS and DSS colitis models." (PMID 37298531, 2023). "Red ginseng fermented with the probiotic L. plantarum decreased IL-6 and TNF-α in the serum and colon tissue and decreased the severity of colitis in DSS-induced colitis mice." (PMID 36986118, 2023). "Increasing evidence has demonstrated that productions of pro-inflammatory cytokines TNF-α, IL-1β and IL-6 are augmented in IBD patients and chemical-induced colitis animal models." (PMID 36830802, 2023). "SM@siRNP can scavenge 2,2-diphenyl-1-picrylhydrazide radical, inhibit NO and proinflammatory cytokine (IL-1β, IL-6, TNF-α), significantly improved the damage of colonic mucosa in DSS-induced colitis mice." (PMID 37033644, 2023). "The results showed that CuET significantly attenuated LPS-induced mRNA levels of TNF-α, IL-1β, and IL-6, consistent with its anti-inflammatory effect on the DSS-induced colitis model." (PMID 37284442, 2023). "L. fermentum improved colitis, reduced TNF- α, IL-1β and IL-6 in serum and induced anti-inflammatory cytokine (IL-10) expression in the colons of DSS-induced colitis mice." (PMID 36986118, 2023). "The levels of TNF-α, IL-6, and IL-1β were increased, and that of IL-10 was decreased after DSS exposure in mice with colitis." (PMID 37047694, 2023). "Recently, Yan-Hong Zhou reported that GBE ameliorates rat inflammatory injury within TNBS-mediated rat colitis models through regulating inflammatory factors (SOD, MDA, TNF-α, NF-κBp65, and IL-6) and antioxidation." (PMID 37111225, 2023). "By contrast to what was herein observed with the acute model of colitis induced by DSS, higher numbers of epithelial apoptotic bodies and increased expression of TNF-α and IL-22 were observed in NOD2▵Lyz2 mice in a T cell-mediated model of ileopathy." (PMID 37876927, 2023). "In a study on the protective effect of CSE on colitis mucosa, T cell regulation was one of the targets of CSE, reducing the oxidative stress level in the intestine, reducing the secretion of TNF-α in the intestinal mucosa, and protecting the intestinal mucosa." (PMID 35923203, 2022). "Recent studies reported that DSS colitis severity is associated with increased production of various inflammatory mediators such as TNF-α, IL-1β, and MPO activity; and IL-10 and TGF-β drive anti-inflammatory response to prevent colitis." (PMID 36193153, 2022). "Consistent with previous studies, our results indicated that GTP inhibited the activity of NF-κB and MPO, the expression of TNF-α, IL-1β, IL-6, iNOS, and COX-2, and the production of NO and PGE2 in colon tissues of mice with DSS-induced colitis." (PMID 35807865, 2022). "A difference (p < 0.05) was also observed between the colitis group treated with HEBD and the colitis group treated with the vehicle, reducing TNF levels to values like the naive group." (PMID 35295931, 2022). "Regarding TNF-α, the mice with TNBS-induced colitis exhibited a significant increase in this pro-inflammatory cytokine." (PMID 36009572, 2022).
colitis (continued). "Serum TNF-α and PGE2 levels, and colonic Tnfa and Il1b mRNA levels were also reduced by supplementation of aloin, Aloe gel, or aloesin to the diets of the rat colitis models." (PMID 35631425, 2022). "Pretreatment with compounds 7b and 13b alleviated the severity of colitis and concomitantly counteracted the increased levels of RORγt, STAT3, CCR6, IL-6, IL-17, IL-23, TNF-α, and PGE2." (PMID 36077306, 2022). "Western blot analysis of TNFα and IL6 in colon samples confirmed an increase in these two proteins in colitis mice, which was suppressed by BBR." (PMID 36528592, 2022). "A potent pro-inflammatory cytokine, TNF-α, was highly upregulated during DSS-colitis and was elevated in intestinal biopsies from CD patients." (PMID 36012618, 2022). "In the Con-DSS group, the expression levels of pro-inflammatory cytokines (TNF-α, IL-6, and IFN-γ) and those of neutrophil-attracting chemokine CXCL2 were increased by colitis." (PMID 35688905, 2022). "Overproduction of pro-inflammatory cytokines, such as TNF-α, IL-1β, and IL-6, is the typical feature of the DSS-induced colitis mouse model." (PMID 36033869, 2022). "The colitis in mice with conditional IEC knockout of NEMO, FADD, CASP8, and RIPK1 mice is largely reversed by TNF or TNFR1 deletion." (PMID 35077396, 2022). "We aimed to investigate the role of rapamycin on the expression of NF-κB p65 and TNF-α in 2, 4, 6-trinitrobenzene sulfonic acid (TNBS)-induced mouse colitis and lipopolysaccharide (LPS)-induced HT-29 cells." (PMID 36032781, 2022). "TNF-α and IFN-γ are major proinflammatory cytokines that synergistically drive epithelial barrier dysfunction and apoptosis, particularly during colitis." (PMID 36144473, 2022). "Increased levels of tumor necrosis factor-α (TNF-α), pentraxin-3, and malondialdehyde (MDA) in colitis group were revealed biochemically." (PMID 36228298, 2022). "Recently, piperine has been shown to inhibit the levels of colonic NF-κB protein and the mRNA expression of pro-inflammatory mediators (TNF-α, IL-1β, IL-6, iNOS, and COX-2) in rats of TNBS-induced colitis." (PMID 35807865, 2022). "ANP downregulated TNF-α, IL-1β, IL-6, IFN-α, and IFN-β mRNA levels in the colonic tissue in the mouse model of colitis (P < 0.05)." (PMID 35280696, 2022). "Interleukin (IL)-6, TNF-α, and IL-12(P40), which have generally been recognized as pro-inflammatory factors in DSS-induced colitis, are activated by antigen-presenting cells to perturb the balance of helper T cells and regulatory T cells." (PMID 35935215, 2022). "In this study, we designed nanoparticles for the delivery of the anti-TNF-α antibody adalimumab (ADA) to target inflamed colonic epithelium and promote local anti-inflammatory immune responses in a murine colitis model." (PMID 35214083, 2022). "A synbiotic composed of AX and L. fermentum HFY06 significantly reversed histopathological changes in the colon and inhibited the activation of the NF-κB signaling pathway and the expression of TNF-α, iNOS, and COX-2, alleviating DSS-induced colitis." (PMID 36518999, 2022). "Our results of ELISA demonstrated that the serum levels of TNF-α, IL-1β and IFN-γ were increased in mice with DSS-induced colitis, but down-regulated after treatment with recombinant IGFBP5." (PMID 36389828, 2022). "The study reported significant reduction in the serum level of IL-6 and TNF-α of LPS-induced, TNBS-induced colitis, and DSS-induced mice group." (PMID 36079752, 2022). "As expected, the plasma levels of proinflammatory cytokines, including tumor necrosis factor alpha (TNF-α), interleukin (IL)-6, and IL-17, were significantly increased in the DSS-induced colitis model." (PMID 36009796, 2022). "In the present study, the levels of IL-6, IL-17A, IL-1β, and TNF-α were increased, accompanied by increased expression of TLR5/MyD88/NF-κB pathway in TNBS induced colitis rats." (PMID 35571126, 2022). "Compared with the normal group, TNF-α, IL-β, IFN-γ and IL-17A obviously increased in colitis tissues." (PMID 35372817, 2022).